CTSB (cathepsin B)
Diseases named in the same sentence as CTSB in open-access papers (continued):
Sharing a sentence is not in itself a finding about the gene and the disease.
tumor (continued). "Furthermore, CSTA is recognized for its ability to inhibit cathepsin B (CTSB), a cysteine protease implicated in the degradation of the extracellular matrix and tumor growth." (PMID 40007784, 2025). "Additionally, the presence of CTSB on the surface of cells in contact with tumour cells facilitates the apoptosis of CD8 + T lymphocytes and the degradation of cytotoxic effector molecules." (PMID 40134439, 2025). "While targeting cathepsin B has demonstrated notable therapeutic benefits in cancer treatment, it is evident that singularly focusing on cathepsin B does not eliminate or suppress tumour growth, emphasizing the complexity of the underlying mechanisms." (PMID 38500921, 2024). "Therefore, the proteolysis of many conjugates was investigated in the presence of cathepsin B, a lysosomal enzyme over-expressed in tumor cells and in rat liver lysosomal homogenate." (PMID 38339141, 2024). "Therefore, we theorize that intracellular pathogens regulate the amount and trafficking of cathepsin B in tumor cells." (PMID 39981299, 2024). "However, mutations in genes CPNE1, CTSB and ELN, indicated that their expression was slightly higher in tumor samples than in normal ones." (PMID 38544823, 2024). "Concentration gradients of specific enzymes, such as matrix metalloproteinases (MMPs), hyaluronidase (HAase), cathepsin B, and esterase, between tumor tissues and normal tissues (usually tumor tissue > normal tissue) can be used as appropriate activators for achieving localized drug release." (PMID 38831883, 2024). "Cathepsin B, implicated in both tumor invasion and metastasis across various cancers, is notably overexpressed in cancers with MYCN gene amplification." (PMID 39981299, 2024). "However, recent advances in imaging tools that target cathepsin B have been proposed, which can help distinguish tumour boundaries and guide surgical early diagnosis of tumours." (PMID 38500921, 2024). "The oxime linkage is non-cleavable (although it slowly decomposes in acidic conditions, especially below a pH of 2), but it has been demonstrated that a small metabolite is released in lysosomal homogenates or in the presence of lysosomal enzyme Cathepsin B, which is overproduced in tumor cells." (PMID 38256168, 2024). "Additionally, CTSB initiates the proteolytic cascade by activating other tumor-promoting proteases, including matrix metalloproteinases and urokinase-type proenzyme activators." (PMID 38203769, 2024). "The upregulation of pro-form CTSB secretion in tumors facilitates tumor progression and metastasis." (PMID 39264885, 2024). "Lysosomal cathepsin B binds to di-arginine residues and is overexpressed in some tumour cells." (PMID 38999115, 2024). "As a prognostic marker and potential therapeutic target in various types of cancer, CTSB is one of the most potent tumor-promoting cysteine cathepsins, overexpressed in various human cancers and secreted by malignant cells and cells of the tumor microenvironment." (PMID 37576397, 2023). "Inhibiting cathepsin B has the potential to slow down tumor growth." (PMID 37111617, 2023). "In the M2-macrophage-like TAMs, OGT directly modifies protease Cathepsin-B at Serine residue 210, which promotes maturation and secretion of Cathepsin-B to the tumor microenvironment to degrade the extracellular matrix supporting metastasis activities of cancer cells." (PMID 37838167, 2023). "In non-tumor diseases, CTSB may act as a secretase involved in the secretory pathway regulated by brain neurons." (PMID 37576397, 2023). "In addition, CTSB is highly expressed in the extracellular space and at the edge of the invading tumor to enhance the invasion and metastasis of cancer cells." (PMID 37576397, 2023). "Similar to the previous study, COX-1/2-degrading PROTACs were specifically released in a cathepsin B-dependent manner, and the released PROTACs provoked COX-1/2 deficiency-associated prostaglandin E2 depletion, followed by the alteration of tumor immunosuppressive environments." (PMID 36839734, 2023).
tumor (continued). "Likewise, this derivative showed inhibition of cathepsin B activity in tumour cells at concentrations of 1.52 ± 0.13 nM (ACHN cells) and 1.76 ± 0.24 nM (Hepa-1c1c7 cells)." (PMID 37233478, 2023). "Finally, we showed that CTSB inhibitor treatment extended the survival of WBBMI1 orthotopic tumor bearing mice compared to placebo treated group." (PMID 37923799, 2023). "CTSB is a direct target gene of miR-140, and overexpression of miR-140 reduces CTSB levels, enhances temozolomide cytotoxicity, inhibits mesenchymal transition, and affects CTSB-regulated tumor spheroid formation and expression of stemness markers." (PMID 37576397, 2023). "However, before describing these therapeutic tools, a brief overview of CtsB activity in physiological conditions and tumor disease is necessary." (PMID 37514035, 2023). "CTSB+ macrophages have been recently shown to repress anti-tumor immune response, suggesting that HIF-2α may drive this function." (PMID 37124241, 2023). "The negative correlation between stefin A and CTSB expression is associated with tumor malignancy and metastasis." (PMID 37576397, 2023). "CtsB overexpression in a tumor can be very prominent and even nearly 50 years ago, it was estimated that the mature active form of this enzyme could represent 20% of the total lysosomal proteases in cancer cells." (PMID 37514035, 2023). "In pathological situations, CTSB promotes angiogenesis when it acts on tumor cells or the ECM." (PMID 37576397, 2023). "However, the promiscuous expression of these genes especially for cathepsin B in tumor cells raises questions related to safety and specificity." (PMID 37064116, 2023). "During tumor development and progression, CTSB has two opposing effects." (PMID 37576397, 2023). "Cathepsin B plays an important role in tumor progression, growth, metastasis, and cell invasion." (PMID 37334378, 2023). "Notably, cathepsin B (lysosomal cysteine protease) is a critical matrix protease involved in tumor metastasis." (PMID 37375411, 2023). "The multi-functional cysteine protease cathepsin B is known to play a role in several biological processes including ferroptosis, tumor cell proliferation and metastasis, lipid metabolism, inflammasome activation, activation of proenzymes, and activation of ion channels." (PMID 37239160, 2023). "Here, we discuss the roles of CTSB in tumor and non-tumor disease pathophysiologies." (PMID 37576397, 2023). "In the presence of cathepsin B at the tumor site, the ACKFRGD peptide was cleaved to expose the 1,2-thiolamino groups of the AC peptide fragment, which would react with CABT via click cycloaddition to form nanoaggregates for enhanced near-infrared fluorescence imaging and MRI." (PMID 37908735, 2023). "Furthermore, we showed that in HCC patients, elevated tumor expression of BMI1 and CTSB strongly associated with poor overall survival, while their expression was positively correlated too." (PMID 37923799, 2023). "In GBM, CTSB is mainly located at the invasive margin of tumor infiltration and neovascularization." (PMID 37576397, 2023). "Therefore, little is known about the relationship between CTSB protease expressed by tumor cells in the treatment of ALL and ASNase sensitivity." (PMID 37446393, 2023). "Another possible reason could be incomplete release of MMAE within tumor cells as a result of a low cathepsin B level in LNCaP cells or even an impaired internalization ratio." (PMID 37239890, 2023). "Additionally, it has been shown that the role of CTSB in oncogenesis can be completely different depending on the tumor type." (PMID 37446393, 2023). "Interestingly, we also showed that in HCC, high tumor expression level of CTSB was correlated with increased incidence of BDTT, whilst HCC patients with high CTSB expression and BDTT exhibited a relatively strong correlation with poor overall survival." (PMID 37923799, 2023).
tumor (continued). "Furthermore, cathepsin activity assays conducted on tumor tissues revealed a dose-dependent decrease in CTSB and CTSD enzymatic activity." (PMID 36097006, 2022). "The degradation of ECM proteins by cathepsin B is required for tumor cell invasion and metastasis." (PMID 35239671, 2022). "We also detected the level of CTSB in serum from tumor mouse model." (PMID 36132145, 2022). "Results show that cathepsin B-induced digestion of nanoparticles into smaller particles might result in better dispersion of the sensitizer in dense tumor formations, as shown by this study." (PMID 35903701, 2022). "Increased expression of cathepsin B in RCC indicates its role in tumor progression." (PMID 36552000, 2022). "Furthermore, upon knockdown of CTSB, the diabetic mice showed a significant reduction in tumor expansion compared to the diabetic mice that had normal CTSB levels, indicating that CTSB was the effector protein of IGF-1." (PMID 36289617, 2022). "With the presence of Cathepsin B, an intracellular cysteine protease that was particularly overexpressed in tumour locations, the H-Phe-Lys-OH peptide could be broken." (PMID 36688039, 2022). "However, the depletion of MMP9 make the tumour cells more invasive and metastatic, a process that is facilitated by the presence of CD11b+ inflammatory monocytes expressing pro-invasive cathepsin B and the secretion of interleukin-6." (PMID 35216069, 2022). "Compared with siRNAs/shRNAs targeting uPAR, siRNAs targeting uPAR and uPA or siRNAs targeting uPAR and cathepsin B exerted a better antitumor effect by inhibiting tumour cell proliferation, migration and invasion and angiogenesis and promoting tumour cell apoptosis." (PMID 35303878, 2022). "In addition, we coupled Pep7 to iRGD using a valine citrulline (Val-Cit) linker which is cleavable by cathepsin B, which is highly expressed in cancer cells to aid in tumor targeting." (PMID 35574389, 2022). "Furthermore, when mice were injected with HCC (HepG2) cells that were silenced in CTSB, tumor size and weight decreased." (PMID 36289617, 2022). "Consequently, FRRG-DOX nanoparticles induce a significant cytotoxicity in cathepsin B-overexpressed tumor tissues by releasing toxic DOX molecules, while DOX release is mitigated in cathepsin B-deficient normal tissues to minimize DOX-related side effects." (PMID 36195911, 2022). "Finally, in non-tumor tissues, the CTSB expression was remarkably (p = 0.0268) enhanced in older patients (>60 years vs. ≤60 years)." (PMID 35563761, 2022). "For GBM, CTSB mainly locates in the invasive margins of tumor infiltration and neovascularization." (PMID 35277559, 2022). "Additionally, we further verified the correlation between CTSB/L and tumor-infiltrating immune cells, and major histocompatibility complex (MHC) molecules in another database TISDB, which has more detailed classifications of the immune cells." (PMID 35155389, 2022). "Accurate assessment of cathepsin B expression in vivo may provide a potential approach for early tumor diagnosis." (PMID 36096856, 2022). "Based on CTSB -catalyzed strategy, Zhang designed a transformable chimeric peptide to target and self-assembled on the cell membrane to encapsulate cells and overcome tumor multidrug resistance (MDR)." (PMID 35186883, 2022). "Importantly, highly accumulated FRRG-MMAE nanoparticles in the tumor tissues via the EPR effect selectively released MMAE molecules in cathepsin B-overexpressed tumor cells, which induced a potent antitumor efficacy by inhibiting tubulin polymerization." (PMID 36297566, 2022). "Lysosomal proteases i.e., cathepsin B are highly expressed on tumor cells." (PMID 34440076, 2021). "Interestingly, PGA can be digested by cathepsin-B, which is a lysosomal protease that is hyper-secreted into the tumour microenvironment of many solid tumours and we and others have demonstrated that this can be exploited in targeted therapeutic approaches." (PMID 33245955, 2021).
tumor (continued). "The effect of CTSB knockdown on tumor growth in vivo was examined in a xenograft nude mice model." (PMID 33628106, 2021). "Importantly, highly accumulated Al-ProD in the tumor tissues via albumin-mediated passive targeting selectively released doxorubicin in cathepsin B-overexpressed cancer cells, which provoked potent antitumor efficacy." (PMID 35056979, 2021). "Moreover, functionalized NPs responded to tumour overexpressed cathepsin B, with following specific enhancement of tumor cell uptake and following DNA damage upon X-ray irradiation." (PMID 33803884, 2021). "Both CREG1 and CTSB are lysosomal proteins, subject to lysosomal sorting, and therefore potentially prone to lysosomal exocytosis in the tumor context; thus, both proteins are spatiotemporally located in the same space, strengthening the idea that such an interaction occurs in vivo." (PMID 32385587, 2021). "In vivo, TAMs promote angiogenesis in PDAC murine tumor model via cathepsin B and S secretion." (PMID 33783686, 2021). "VEGF secretion by cancer cells and in tumor is regulated by cathepsin via an unknown mechanism and could explain the positive impact of cathepsin B on tumor angiogenesis." (PMID 33783686, 2021). "Inhibition of tumor weight and tumor volume by CTSB-shRNA was observed in vivo." (PMID 33628106, 2021). "During breast cancer progression, tumor cells acquire resistance to acid-induced toxicity and extracellular matrix degradation through the release of cathepsin B into the tumor microenvironment, providing for acid-mediated tumor invasion with altered glucose metabolism." (PMID 33816282, 2021). "Furthermore, VEGF protein level is higher in breast tumor from mouse PyMT overexpressing cathepsin B than that in tumor from PyMT WT mice." (PMID 33783686, 2021). "To address these questions and to identify CTSB-regulated proteins in the tumor microenvironment, we employed the transgenic MMTV-PyMT mouse model for metastasizing breast cancer in which we have previously performed extensive CTSB loss- and gain-of-function studies." (PMID 32385587, 2021). "(iii) Cathepsin B. The tetrapeptide linkage Gly-Phe-Leu-Gly is mostly employed in the design of enzyme-responsive, polymeric systems, as this group is easily cleaved by cathepsin B, an lysosomal enzyme, which is typically overexpressed in tumor tissues." (PMID 32580366, 2020). "The polymer backbone would be degraded into small fragments in the presence of overexpressed cathepsin B in the tumor cellular microenvironment and the small fragments would be cleared to avoid toxic buildup of the delivery vector and the MRI contrast agent in the body." (PMID 32195104, 2020). "Interestingly, CTSB has been also shown to promote epithelial–mesenchymal transition (EMT) in tumor cells and contribute to tissue fibrosis." (PMID 33379277, 2020). "A preclinical study of the tumor model in mice indicated that broad-spectrum inhibitors targeting CTSB and other cysteine cathepsins could effectively inhibit the proliferation of tumors." (PMID 33238959, 2020). "In vivo, PNS could directly inhibit the expression of the CTSB gene in tumors of mice, limit tumor growth, and alter tumor-related indices, such as CEA, NSE, and CYFRA21 levels, in the serum to different extents simultaneously." (PMID 33238959, 2020). "Cystatin C is an important inhibitor of cathepsin B and tumor cell invasion." (PMID 32180899, 2020). "Interference with RNA transcription of cathepsin B reduces tumor aggressiveness." (PMID 33335896, 2020). "Indeed, in cancer, cathepsin B is secreted by tumor cells where it contributes to the degradation and remodeling of the extracellular matrix and whereby facilitating tumor cell invasion into the surrounding tissue." (PMID 31484396, 2019). "CTSB knockdown also suppressed tumor cell proliferation as compared to controls (P < 0.01)." (PMID 30796200, 2019). "This leads to production of CTSB which can promote tumor growth." (PMID 30796200, 2019).
tumor (continued). "Taken together, upregulation of cathepsin B within WHO grade 1 MG may indicate a growth phase in this tumor, although, this requires further investigation." (PMID 30949483, 2019). "Given the abnormal expression of Cathepsin B enzyme in a spectrum of tumours, as well as the ubiquitous metabolic phenotype of cancer cells, the strategy demonstrated here could have implications in cancers of various types." (PMID 31296864, 2019). "Likewise, 75% (30/40) of GBC cases also exhibited higher CTSB expression (H-score >4) in tumor endothelial cells as compared to only 11% (7/60) of controls, implying significant overexpression of CTSB protein (p < 0.0001) in this malignancy." (PMID 31824841, 2019). "Previous data suggest roles for CTSB in tumor invasion and metastasis." (PMID 30796200, 2019). "Cathepsin B has been established as a biomarker for tumor angiogenesis and metastasis." (PMID 29455656, 2018). "Cathepsin B, a cysteine protease, has been shown to play a role in tumor growth and invasion." (PMID 30344926, 2018). "Additionally, cathepsin B enhances tumor progression by proteolytic degradation of the metalloprotease inhibitors, TIMP-1 and TIMP-2, and by release of growth factors VEGF and TGF-β1 bound to the ECM proteins." (PMID 28938624, 2017). "CTSB-overexpressing cells were observed mainly in tumor areas with high NS1 reactivity." (PMID 28967558, 2017). "Interestingly, increased levels of the lysosomal protease cathepsin B can be found in the serum of cancer patients and inhibition of proteolysis slows tumor invasion in vitro." (PMID 28978320, 2017). "MMP2, MMP3, MMP9, uPA and Cathepsin B play critical roles in tumor invasion and metastasis." (PMID 29137230, 2017). "In NOD/SCID mice, cathepsin B was consistently located at the invasive edges of the GBM tumor." (PMID 28424417, 2017). "Moreover, paracrine IL-6 signaling between DCIS cells and CAFs promotes tumor cell growth and migration in part through cathepsin B-mediated ECM degradation." (PMID 28506312, 2017). "Cathepsin B expression is not limited to the lysosome, particularly in tumour cells." (PMID 29065110, 2017). "Our study suggests that high level of CTSB expression might be positively correlated with worse tumor biological features, such as rapid tumor progression and metastases." (PMID 26896959, 2016). "The results indicate that CTSB is able to promote HCC tumor growth in nude mice." (PMID 26896959, 2016). "CTSB expression was significantly correlated with stage, recurrence, and tumor differentiation." (PMID 26896959, 2016). "Acidic extracellular pH (pHe) and growth factor signaling drive anterograde (plus end or peripheral) lysosome trafficking, and we have previously demonstrated that the spatial distribution of lysosomes within tumor cells dictates secretion of cathepsin B and invasiveness." (PMID 27105540, 2016). "Furthermore, cathepsin B mRNA levels correlated with fat-free mass index and tumor stage and were higher in cancer patients who were smokers." (PMID 26856534, 2016). "Additionally, we have shown that CTSB expression was correlated with stage, recurrence, and tumor differentiation." (PMID 26896959, 2016). "Previous work determined that treatment with acidic pHe of 6.4 was sufficient to induce lysosome trafficking which paralleled lysosome secretion, including the release of cathepsin B into the extracellular environment, a lysosomal protease that contributes to matrix degradation and tumor invasion." (PMID 26784896, 2016). "In addition, CTSB is upregulated in premalignant lesions and various pathological conditions, such as tumor invasion, rheumatoid arthritis, and osteoarthritis." (PMID 27031837, 2016). "Observation that troglitazone prevents invasion in prostate cancer cell after extracellular acid pH stimuli, lead to the demonstration that Rab7 is the negative regulator of cell surface-directed lysosome trafficking, determining abrogation of cathepsin B secretion and tumor cell invasion." (PMID 27548222, 2016).